LEP (leptin)
Diseases named in the same sentence as LEP in open-access papers (continued):
Sharing a sentence is not in itself a finding about the gene and the disease.
Insulin resistance (continued). "Thus, based on our data, we suggest that the GA and AA genotype carriers might be a risk factor for T2DM as opposed to those carrying the GG genotype, which is in agreement with the hypothesis that leptin has a potent role in the development of insulin resistance among T2DM patients." (PMID 35334523, 2022). "Studies on synthetic PPAR antagonist showed that blocking or reducing the activity of PPARγ can reduce HFD-induced adipocyte hypertrophy and insulin resistance by reducing the size of adipocytes and decreasing the secretion of TNF-α and leptin." (PMID 34721992, 2021). "In particular, genes whose transcription supresses insulin resistance and T2DM, such as CD36, adiponectin, adipsin, and leptin, are downregulated by Thrap3 binding to pPPARγ." (PMID 34339734, 2021). "In a group of obese children with insulin resistance, there was a positive correlation between the level of asprosin and WHR, HOMA-IR and the ratio of leptin to adiponectin." (PMID 34539448, 2021). "Maternal fasting glucose, insulin, homeostatic model assessment of insulin resistance (HOMA-IR), leptin, TNF-alpha, C-reactive protein, adiponectin, and lipids are measured by trained staff at each research site, following the established protocols." (PMID 33827659, 2021). "Our study identified increased leptin and resistin levels in HFCD rats suggesting the presence of insulin resistance." (PMID 34037093, 2021). "According to previous studies, low levels of leptin and high levels of TNF-α lead to insulin resistance." (PMID 34922625, 2021). "In the context of SD, glucose, insulin, and leptin levels and HOMA-IR2 (homeostatic measure of insulin resistance) index were significantly reduced at the end of the VLCI period in LCC and FMD mice." (PMID 34753921, 2021). "In this study, NAG-1 Tg mice exhibited downregulated expression of leptin in the WAT, BAT, and muscle and decreased insulin resistance compared with WT mice." (PMID 34294853, 2021). "In the hypothalamus, metabolism enhancing TTR expression was upregulated, and the PTPN1 level denoting insulin resistance was downregulated, while NPY, AGRP, POMC, CART levels denoting leptin resistance showed a normalizing trend." (PMID 32943760, 2021). "A variety of adipokines, such as leptin and MIF, are related to the occurrence of insulin resistance." (PMID 34485124, 2021). "As for the serum metabolic parameters, the CAF diet induced an increase in circulating levels of triacylglycerides, insulin, insulin resistance indicated by the HOMA-IR (p < 0.05), and leptin (p < 0.001), compared to the STD group." (PMID 34960026, 2021). "IL-6 and SOCS3 mediate inflammatory responses and the satiety hormone of leptin, induce dysfunction of Jak-STAT signaling pathway, leading to insulin resistance and lipid metabolic disorders." (PMID 32106651, 2021). "While HFD-induced reduction in adiponectin was significantly improved by GML supplementation, the sensitivity of another adipocytokine, leptin, was also modulated, which induced hepatic expression of TNF-α and insulin resistance." (PMID 32265324, 2020). "Then, blood levels of leptin, adiponectin, and LAR (an indicator of insulin resistance) were measured." (PMID 33680012, 2020). "Ramadan intermittent fasting decreased adiponectin and increased leptin, LAR, insulin, and insulin resistance in both Type 2 DM and FDRs as well as decreased GH in both FDRs and healthy controls and increased hs-CRP in healthy controls." (PMID 32775407, 2020). "Leptin and adiponectin alterations in T2DM influences the adipose tissue function and increases insulin resistance." (PMID 33680012, 2020). "There is a network of factors that, in addition to the action of LPS, contributes to the development of insulin resistance, such as elevated plasma levels of FFA and mitochondrial dysfunction and hormone levels (reduced adiponectin or leptin resistance)." (PMID 32633894, 2020).
Insulin resistance (continued). "In the current study, combination of both hormones stimulated more Akt phosphorylation than either leptin or galanin alone did, which may be blocked by MK‐2206, suggesting that Akt was necessary for the cooperative effects of both hormones on alleviation of insulin resistance." (PMID 32395890, 2020). "Primary endpoints were the effects on body mass index standard deviation score (BMI-SDS) and homeostatic model assessment of insulin resistance (HOMA-IR), key secondary endpoints were the levels of C-reactive protein (CRP), leptin, and adiponectin." (PMID 32154197, 2020). "Altered secretions of adipokines such as adiponectin (ADIPOQ), leptin (LEP) and resistin (RETN) by adipose tissues is one of the important contributory factors to insulin resistance, cardiovascular diseases and metabolic disorders." (PMID 32695266, 2020). "Moreover, in the second trimester, in addition to the positive associations of IL-6 and leptin with insulin resistance, NGF was closely related to glucose metabolism, insulin resistance and pancreatic β cell function and might be a protective factor in the pathological process of GDM." (PMID 33292292, 2020). "Glucose, insulin, leptin, and visfatin levels in sera, as well as the homeostatic model assessment insulin resistance (HOMA-IR) score, which is a measure of insulin resistance, were collected." (PMID 33381605, 2020). "In particular the individuals with syndrome X have extensive visceral fat, insulin resistance, hypertension (high ATII levels), high leptin levels and can also be leptin resistant." (PMID 32844126, 2020). "Circadian disruption, especially constant darkness, induces insulin resistance of PCOS in rats, including increased fasting blood glucose level and increased serum insulin and leptin levels." (PMID 32334629, 2020). "Leptin is thought to participate in both NAFLD/NASH progression, by contributing to the development of insulin resistance (IR) and steatosis and subsequently inducing fibrosis." (PMID 31947953, 2020). "Leptin is also an adipocytokine synthesized and secreted specifically by WAT and has peripheral actions that contribute to type 2 diabetes, insulin resistance, and atherosclerosis." (PMID 32796650, 2020). "Cardiometabolic biomarkers (glucose, insulin, homeostasis model assessment-estimated insulin resistance (HOMA-IR), HOMA β-cell function, and leptin) and RBC hemorheological parameters (RBC deformability and aggregation) were analyzed." (PMID 31835508, 2019). "AM-Ex supplementation reduced insulin resistance, serum triglyceride, LDL- and total cholesterol levels, white fat tissue weights, and leptin levels." (PMID 31137884, 2019). "Female adolescents with high BF% (G2 and G3) had higher NC, WC, WHtR, and percentages of gynoid and android fat, as well as higher insulin resistance index (HOMA-IR), insulin, and leptin concentrations." (PMID 31933541, 2019). "This lowering of plasma leptin, combined with the increase in glucocorticoid, as well as the profound increase in visceral adiposity could all contribute to elevation of triglyceride storage in the liver, which together with insulin resistance, are hallmarks of the metabolic syndrome." (PMID 30860981, 2019). "Administration of high-fructose-fed (65% kcal/diet) Wistar rats with curcumin (200 mg/kg b.w./day) for 8 weeks resulted in significantly reduced serum glucose, insulin, leptin and TNF-α levels and HOMA-IR, indicating reduced insulin resistance." (PMID 31881654, 2019). "Materials and Methods: Twenty-four obese subjects were investigated for body mass index (BMI), total fasting BA, insulin, homeostasis model assessment of insulin resistance (HOMA-IR), and leptin before and at 7 and 30 d after SG." (PMID 31766784, 2019). "In accord with this, our present data suggest that leptin replenishment by fat transplantation to Lepob/ob mice ameliorated hypersecretion of GIP, as well as insulin resistance." (PMID 31509948, 2019).
Insulin resistance (continued). "When periods of overnutrition are sustained, abnormal production of adipocytokines (e.g., leptin, adiponectin, and TNF-α) or hepatokines with diabetogenic properties (e.g., fetuins, RBP4, and selenoprotein P) intensify peripheral insulin resistance." (PMID 31771244, 2019). "Two more genes supporting these mechanisms of insulin resistance were found here among the most overexpressed genes: HTRA4 (IGF binding domain containing protein, fold-change = 7.33) and LEP (leptin, fold-change = 4.89)." (PMID 31998361, 2019). "Blood glucose, asprosin, irisin, leptin, adiponectin, and insulin were measured before and after 20 WBC treatments, after which a homeostasis model assessment of insulin resistance (HOMA-IR) and atherogenic index of plasma (AIP) were calculated." (PMID 31510055, 2019). "MS rats had increased systolic blood pressure, triglycerides, insulin levels, insulin resistance index homeostasis model (HOMA), adiponectin, and leptin." (PMID 30987086, 2019). "Decreased abundance of IR and elevated expression of Leptin, IRS1, and Glut4 have confirmed that continuous light impairs glucose metabolism and contributes to the insulin resistance in PCOS rat models." (PMID 32038578, 2019). "Indeed, decreased affinity and IgG binding to leptin associated with hyperinsulinemia and insulin resistance were found in both groups of diabetic patients, but not in obese and healthy controls, indicating that loss of binding affinity of leptin-reactive IgG is favorable for T2D." (PMID 29795184, 2018). "Insulin resistance (estimated by the HOMA-IR index) decreased significantly, with concomitant reductions of adipsin and leptin." (PMID 29075849, 2018). "Homeostasis model assessment adiponectin (HOMA-AD), Homeostasis model assessment insulin resistance (HOMA-IR), and adiponectin/leptin ratio (ALR) were used to identify IR." (PMID 29694637, 2018). "Levels of fasting blood glucose, serum insulin, C-peptide or leptin, and HOMA-IR index representing insulin resistance that were increased in HFD-fed mice were significantly lowered by MSL-7 administration for 8 weeks." (PMID 29650965, 2018). "The relative ratios of studied adipokines (e.g. resistin/RBP4, leptin/MCP-1 and MCP-1/RBP4) are correlated with fasting glucose and HbA1c levels as well as with insulin resistance/sensitivity and β-cell function indexes." (PMID 29785210, 2018). "HFB-fed mice showed signs of impaired glucose metabolism and insulin resistance along with a significant elevation in the concentration of triglycerides, LDL-cholesterol, total cholesterol, IL1β, TNF-α, IL-6, and leptin in serum." (PMID 30319558, 2018). "Triglycerides, insulin, homeostasis model assessment-insulin resistant (HOMA-IR), leptin, C-reactive protein (CRP), and EDF marker intercellular adhesion molecule 1 (ICAM-1) were significantly higher in obese children and adolescents." (PMID 30572569, 2018). "In this study, the authors assessed the coronary calcium score, homeostatic model assessment for insulin resistance (HOMA-IR), and serum adipocytokine (leptin, adiponectin, resistin, and visfatin) levels in 169 RA patients." (PMID 30584543, 2018). "Placental leptin production is increased in GDM, probably as a result of placental insulin resistance, and this further contributes to hyperleptinemia." (PMID 30373146, 2018). "The present study aims to investigate the levels of leptin, resistin, visfatin, SFRP5, MCP-1/CCL2, and RBP4 as well as their correlations with insulin resistance and clinical parameters of overweight and T2DM in a Vietnamese study group." (PMID 29785210, 2018). "To examine the role of adipocyte hormones and LPS in insulin resistance in HIV patients, we investigated the role of adiponectin, leptin, visfatin and LPS levels in the insulin resistance of HIV-infected patients treated with HAART." (PMID 29434676, 2018).
Insulin resistance (continued). "BTS increased mRNA expression levels of leptin, adiponectin, and UCP1 in brown adipose tissue and improved insulin resistance in obese mice fed a high-fat diet." (PMID 28360931, 2017). "TZDs can decrease the insulin resistance, modify the adipocyte differentiation, inhibit the VEGF-induced angiogenesis, decrease leptin levels (perhaps leading to an increased appetite) and have the effects of anti-inflammatory." (PMID 28770353, 2017). "Leptin overexpression was found responsible for TNF-α and IL-6-related chronic inflammation, insulin resistance, liver fibrosis, and HCC development." (PMID 27703473, 2016). "Accordingly, leptin, retinol binding protein 4 (RBP4), adiponectin and several other adipocytokines are reported to play a role in the regulation of insulin resistance and lipid metabolism." (PMID 26924713, 2016). "All were evaluated for anthropometric parameters, blood pressure, metabolic variables, homeostatic model assessment of insulin resistance (HOMA-IR), adiponectin, leptin, C-reactive protein, and genotyping." (PMID 26561012, 2015). "Leptin is involved in the pathogenesis of GDM through regulating the secretion of estrogen, progesterone, androstenedione and other hormones relating to insulin resistance." (PMID 26000008, 2015). "In the present model, liver hepcidin expression and serum leptin were enhanced in the HFD group, and these mice also demonstrated insulin resistance." (PMID 25569627, 2015). "In skeletal muscle, leptin can impair GLUT 4 translocation, which contributes to insulin resistance." (PMID 26578976, 2015). "First, BMI percentile was positively correlated with insulin resistance (fasting insulin and HOMA-IR), lipid profiles (LDL-c, TG and TC), and inflammatory markers (hs-CRP, MCP-1, TNF-α, PAI-1, and leptin) but negatively correlated with adiponectin level." (PMID 26011530, 2015). "In this study, we demonstrated that HFD will induce insulin resistance (higher OGTT, leptin and F2-isoprostane, and lower adiponectin levels), partly through transcriptional modulation of insulin signaling genes." (PMID 26273674, 2015). "We analyzed the correlations of glucose tolerance and insulin resistance with the fasting levels of 10- and 12-(Z,E)-HODE/LA, RBP4, glycoalbumin, adiponectin, leptin, and hs-CRP." (PMID 26132231, 2015). "OVX diabetic females suffer from serious metabolic disturbances, suggested by exacerbation of insulin resistance in terms of disrupted lipid profile, higher HOMA-IR, hyperinsulinemia, higher leptin, and lower adiponectin concentrations." (PMID 25834745, 2015). "The aim of this study is to assess the concentrations of the leptin and the sOB-R in PCOS and its relation to adiposity, insulin resistance, and androgens." (PMID 26180527, 2015). "In the correlation analysis, BMI percentile was positively correlated with insulin resistance (fasting insulin level and HOMA-IR) and inflammatory markers (hs-CRP, MCP-1, TNF-α, PAI-1, and leptin levels) but negatively correlated with the adiponectin level." (PMID 26011530, 2015). "High fructose diet increased lipogenesis, leptin resistance, intra-abdominal fat storage, hunger rating, energy intake, CRP concentration, blood pressure, and induced impaired fasting glucose by insulin resistance in the liver and adipose tissue." (PMID 26225136, 2015). "Thus, a lack of mGluR5 might reduce susceptibility to diet-induced insulin resistance, since mGluR5−/− mice show decreased plasma levels of leptin and insulin, despite a 10-week high-fat diet." (PMID 24847259, 2014). "The further study will focus on whether prenatal exposure to LPS and High-fat diet cause change in maternal serum leptin level, and whether maternal exposure to LPS and high-fat diet only during pregnancy produce offspring without both hypertension and insulin resistance." (PMID 24498431, 2014).
Insulin resistance (continued). "After adjusting for age and gender, SMI and CRF tended to be negatively correlated with most of the markers for insulin resistance and chronic inflammation, including HOMA-IR, hsCRP, IL-6, leptin, and the number of metabolic syndrome components." (PMID 24937121, 2014). "Regarding the markers for insulin resistance and chronic inflammation, there were significant differences in HOMA-IR, hsCRP and leptin levels between those with combined low muscle mass and visceral obesity and the normal group in both men and women." (PMID 24937121, 2014). "It has also been reported that prolactin is involved in insulin resistance in WAT during lactation and suppresses insulin-induced leptin production in WAT." (PMID 24299740, 2014). "In addition, leptin-related hyperphagia is closely associated with the development of insulin resistance in this model, which may not be relevant to the situation in humans." (PMID 24809394, 2014). "A significant positive correlation between leptin and HOMA in patients with lipodystrophy demonstrated the role of this adipokine in insulin resistance." (PMID 24958357, 2014). "Waist circumference, blood pressure, HOMA insulin resistance (HOMA-IR) and plasma levels of fasting glucose, triglycerides, HDL cholesterol, LDL cholesterol, total cholesterol, insulin, and leptin were measured in the offspring." (PMID 23741411, 2013). "It must be noted that leptin, IL6 and TNF are pro-inflammatory cytokines with a recognised role in the development and progression of insulin resistance, T2DM and cardiovascular disease." (PMID 23298335, 2013). "The results obtained with the multiplex gut hormone panel were reassuring with regard to the roles of insulin resistance and metabolic dysfunction in AD because they reported AD Braak stage declines in insulin and GLP-1, and increases in leptin." (PMID 25035815, 2013). "TA effectively prevented HF diet-induced increases in the levels of blood glucose, insulin, leptin and HOMA-IR index (p < 0.001, p < 0.05, p < 0.05, p < 0.01, respectively) and attenuated insulin resistance." (PMID 23455665, 2013). "Recent data has focused on the roles of adipose tissue-derived mediators, such as adiponectin, leptin, resistin, tumor necrosis factor-alpha (TNF-α), visfatin, apelin, and chemerin in the pathogenesis of insulin resistance and inflammation." (PMID 23691290, 2013). "Interestingly, the proposed mechanism involved in sarcopenic obesity could be the increased production from adipose tissue of different substances, such as tumor necrosis factor-α (TNF-α) and leptin, which are known to influence insulin resistance and growth hormone (GH) secretion." (PMID 23690769, 2013). "Indeed, preclinical and clinical experiments showed that obese rodents and humans displayed leptin resistance that may directly contribute to the reduction of lipid oxidation in insulin-sensitive organs, leading to accumulation of lipids and insulin resistance." (PMID 24455420, 2013). "The patterns of decreasing adiponectin, decreasing adiponectin/leptin ratio, and increasing TNF-α are consistent with increasing insulin resistance observed in this species." (PMID 24198811, 2013). "Leptin and FFA, two bioactive molecules mainly produced in adipocytes, contribute to insulin resistance and are important regulators between tissues." (PMID 24312573, 2013). "The effect of leptin on inducing insulin resistance was exhibited by positive correlation between mean HOMA-IR and leptin (P < 0.05, r = 0.76) in this research." (PMID 23251156, 2012). "NO distillate administration reduced fasting blood glucose, HbA1c, insulin resistance, total cholesterol, low density lipoprotein, atherogenic index, triglyceride-HDL ratio, insulin, and leptin levels." (PMID 23251156, 2012).